FAP (fibroblast activation protein alpha)
Diseases named in the same sentence as FAP in open-access papers (continued):
Sharing a sentence is not in itself a finding about the gene and the disease.
tumor (continued). "Our findings that FAP is expressed on the NK cell surface suggests that anti-FAP/IL-2 fusion protein may also target IL-2 directly to NK cells, enhancing NK cell activation and potentially tumor clearance." (PMID 38196606, 2023). "In combination with the analysis results, COL10A1/FAP/FN1 were mainly positively correlated with most of the tumor immune cells, which might be associated with an enhanced tumor immune response." (PMID 38063927, 2023). "Finally, FAP NPs with an α-disulfide bond showed the most outstanding antitumor effect, which was attributed to higher reductive responsiveness and faster tumor-specific drug release than FBP NPs and FGP NPs." (PMID 36986645, 2023). "Additionally, FAP contributes to tumorigenesis and tumor immunity by modulating the infiltration of immune cells." (PMID 37490719, 2023). "In addition, much lower level of mRNA expressions of CXCL12 which mainly produced by CAFs in the tumor site was observed in the FAP-mBBZ CAR-T group than those from CLDN18.2-mBBZ CAR-T and UTD groups." (PMID 37046312, 2023). "Moreover, when chemotherapy drugs were applied in FAP-vaccinated mice, the absorption of chemotherapeutic drugs became 70% higher, tumor growth was strongly suppressed, and the lifespan got much longer." (PMID 37316886, 2023). "Second, our study laid the foundation for detailed studies of the correlation between FAP expression and diverse immune cell infiltrations, first revealing the role of FAP on inducing M2 macrophages polarization to promote tumor progression across gastrointestinal cancers." (PMID 37325617, 2023). "In cancer, FAP-α has been reported to induce tumor angiogenesis, growth and invasion." (PMID 37686317, 2023). "In addition to macrophages and myeloid dendritic cells, FAP can also block the anti-tumor response through regulating T cell attraction, differentiation, and retention through various immunosuppressive checkpoint proteins and cytokines." (PMID 37166418, 2023). "In summary, IL2-7NP2-TNFmut showed encouraging tumor-homing properties in lesions expressing cell membrane-bound FAP, a target that has been extensively validated by nuclear medicine procedures as an excellent accessible marker of various types of solid malignancies." (PMID 37092450, 2023). "However, with the elimination of CAFs in TME, the antitumor effect of FAP-targeted CAR-T cells against tumor cells is limited; thus, the tumors grow resistant to the treatment." (PMID 37046312, 2023). "PSMA inhibitor-based tracers can basically only be applied in prostate cancer and octreotide-based SSTR-targeting tracers for neuroendocrine tumors (NETs), while targeting FAP allows for a broader application in many different types of cancers, which makes it a more universal pan-tumor target." (PMID 36980775, 2023). "These three types can be separated by the biomarkers of myCAF, which exhibits the high expression of ACTA2, FAP, and TGF-β, and low expression of IL6, which requires direct interaction with cancer cells in PDAC and might be associated with tumor progression." (PMID 36900272, 2023). "Moreover, the IHC of tumor tissues showed that FAP was also expressed in the extracellular matrix and cytomembrane." (PMID 36382346, 2023). "The study suggested that increased angiogenesis and immunoregulation of TME may be induced by FAP expression in CRC stroma that eventually promotes tumor growth in this cancer." (PMID 37316886, 2023). "Additionally, there was a linear correlation between FAP expression in the tumor stroma and [68Ga]FAPI-04 PET uptake." (PMID 38011131, 2023). "Even in the case of the promising multi-specific anti-CD40 DARPin construct, activated by fibroblast activation protein (FAP) at the tumor site, an interaction of soluble CD40 may occur and should be considered for future studies." (PMID 37838778, 2023).
tumor (continued). "In HNSCC xenograft models, treatment with a novel anti-FAP monoclonal antibody-maytansinoid conjugate (FAP5-DM1) resulted in sustained suppression of tumour progression with excellent efficacy and tolerability." (PMID 36980527, 2023). "In contrast, the free ICG group presented no fluorescence signals in the tumor site, demonstrating that FAP-2286-ICG could predominantly improve the tumor-targeting ability and possess longer tumor retention behavior." (PMID 38026901, 2023). "PTK7, SERPINH1, and FAP could discriminate PanIN versus tumor‐related stroma by contrast to αSMA and LRRC15." (PMID 36587397, 2023). "On the other hand, FAP knockdown blocked the transition of tumor cells from G1 to S phase." (PMID 38313431, 2023). "Additionally, we found that the downregulation of FAP was effective at slowing tumor progression in vivo." (PMID 37752545, 2023). "Moreover, the expression levels of FAP in CAFs are significantly correlated with Lauren's classification, degree of differentiation, depth of tumour invasion, and TNM stage 24." (PMID 37649615, 2023). "According to mechanistic analysis, eNVs-FAP stimulated dendritic cell maturation, increased infiltration of effector T cells into tumor cells and FAP+ CAFs and decreased the number of immunosuppressive cells such as M2-like TAMs, myeloid-derived suppressor cells, and Tregs in the TME." (PMID 37496657, 2023). "The imaging and biodistribution analysis of mice co-injected [68Ga]Ga-SB04028 with FAPI-04 (0.5 mg/mouse) revealed a ~97% reduction in the tumor uptake (10.1 ± 0.42 %ID/g vs. 0.30 ± 0.04 %ID/g) substantiating in vivo FAP specificity of our lead candidate [68Ga]Ga-SB04028." (PMID 37375746, 2023). "Furthermore, the number of tumor metastases were significantly decreased by the FAP-α antibody conjugated system compared to that with the negative control siRNA nanocomplex." (PMID 37627173, 2023). "Moreover, the correlation between FAP-positive CAFs and the expression of 5-LO, which is thought to be involved in tumor immunity, was examined." (PMID 38017374, 2023). "Additionally, FAP positive tumors more frequently displayed elevated numbers of tumor-infiltrating CD3-positive T-lymphocytes [p = 0.014; Wilcoxon rank-sum test with ordinal CD3 values; p = 0.027, Fisher’s exact test with grouped CD3 values (high/low)]." (PMID 37614665, 2023). "In addition to the findings above, in this study FAP positivity also correlated with high expression of CD3 on T-lymphocytes in the tumor stroma of CRC." (PMID 37614665, 2023). "In the majority of human solid cancers, the expression of FAP is observed in a selective manner among cancer-associated fibroblasts (CAFs) and pericytes, while tumor cells do not exhibit this expression." (PMID 37864148, 2023). "Thus, FAP-targeted CAR-T cells are likely to attack CLDN18.2-positive tumor cells at the initial stage of treatment in our animal experiment by this mechanism." (PMID 37046312, 2023). "FAP plays an important role in tissue remodeling and aids tumor cells development by multiple mechanisms, including immunosuppression, drug resistance, stem cell promotion, promoting invading surrounding tissue, proliferation, angiogenesis, and epithelial-to-mesenchymal transition." (PMID 37316886, 2023). "This combination strategy markedly reduced primary tumor progression and significantly extended mice survival, thus validating the therapeutic advantage of FAP CAR T-cell treatment prior to tumor antigen targeting CAR T-cell administration for stromal solid tumors." (PMID 37251405, 2023). "FAP is a serine protease notorious for its heightened expression in tumor stroma." (PMID 36674595, 2023). "In particular, since 2018, researchers from the University of Heidelberg showed that DOTA-containing FAP inhibitors (FAPI) can be coupled with Gallium-68 and used for diagnostic PET imaging of multiple tumor entities, such as breast, colon, lung and pancreatic cancer." (PMID 36765866, 2023).
tumor (continued). "We extrapolated that MFAP5 + fibroblasts could drive tumor development by signal coordination with FAP + fibroblasts." (PMID 37344903, 2023). "We speculate that several factors may contribute to the variable tumor uptake of the FAP-targeted agent." (PMID 38026901, 2023). "IHC staining of the fixed tumor tissues confirmed high FAP expression in HT1080-FAP tumors." (PMID 38706713, 2023). "Furthermore, the correlation between BRAF, KRAS, NRAS mutations, and FAP and CXCR4 in both the primary tumor and the first metastasis were examined." (PMID 37892020, 2023). "The radiohybrid strategy, exploiting SiFA and DOTAGA chelator, may serve as useful platforms to design and create theranostics ligands for treatment of FAP-positive tumor." (PMID 36864362, 2023). "The mechanism that aberrant FAP expression promotes tumor progression probably lies in two main hypotheses." (PMID 37166418, 2023). "FAP overexpression also promotes tumor growth in some cancers." (PMID 37316886, 2023). "FAP overexpression has been shown to enhance tumor development in a mouse model which may afterwards be decreased by anti-FAP antibodies." (PMID 36813980, 2023). "Tracers against FAP have been developed and showed selective tumour uptake." (PMID 36480035, 2023). "Importantly, FAP overexpression enhances NK cell invasion through matrix, promoting tumor infiltration both in vitro and in vivo." (PMID 38196606, 2023). "In addition, FGF20 protein detection overlapped with FAP protein in PanCK(-) areas at EOCC tumor invasive margin." (PMID 37964075, 2023). "Results showed that medium from FAP-overexpressed LX2 cells could promote tumor cell migration as well as invasion process." (PMID 37325617, 2023). "Some studies suggest that FAP promotes the proliferation of tumor cells." (PMID 36382346, 2023). "Due to the high selective expression of FAP in the tumour microenvironment and its involvement in key processes of tumour growth and survival, it has become an interesting molecular target for the development of cancer therapies and diagnostics in recent years." (PMID 37631053, 2023). "It should be noted that this study was conducted with very small sample sizes, and the association between FAP expression and tumor location is not assessed." (PMID 37316886, 2023). "The tumor takes advantage of FAP in a “static” phase of its growth." (PMID 37892020, 2023). "Despite all this, the real role of these FAP gene alterations in human cancers remained uncertain, and a larger mutant sample size should be required to further explore the impact of these genetic alteration on tumor progression." (PMID 37166418, 2023). "As a vital component of the tumor microenvironment, FAP plays a crucial role." (PMID 37583569, 2023). "In addition, 177Lu-FAP-2287 had a significant impact on tumor weight at 746 mg compared to vehicle control on day 13 pi (P = 0.0048)." (PMID 37086273, 2023). "Since 2018, imaging fibroblast activation protein (FAP) expression in tumor microenvironment utilizing fibroblast activation protein inhibitors (FAPi) labeled with gallium-68 has gained interest and an increasing number of studies have attempted to explore this modality in various cancers." (PMID 37111277, 2023). "Notably, we showed BM-MSCs homing into TNBC TME, their trans-differentiation in cancer-associated fibroblasts with high levels of α-SMA, FAP and FSP-1 when co-cultured with TNBC cells and, consequently, their support in metastatic spread of tumor cells." (PMID 36672233, 2023). "This is because faster clearance from the blood pool reduces their chances to bind to FAP in tumors and might result in a relatively lower overall tumor uptake." (PMID 36986548, 2023). "Moreover, a remarkably high and specific accumulation of radiolabeled FAP-targeting TMs at the tumor site of xenograft mouse models was observed." (PMID 38102692, 2023). "Additionally, FAP overexpression enhances NK cells invasion into a human tumor in immunodeficient mice." (PMID 38196606, 2023).
tumor (continued). "Based on the PI3K/Akt and WNT pathways upregulation observed at the EOCC tumor invasive margin using spatial analysis, we sought to identify potential intercellular crosstalk between PanCK(+) tumor epithelial cells and FAP(+) CAFs at the EOCC tumor invasive margin." (PMID 37964075, 2023). "We next investigated whether FAP-CAR T cells can augment anti-tumor immunity of subsequent administration of Meso-CAR T cells." (PMID 37607999, 2023). "Notably, FAP-mBBZ CAR-T cells had better antitumor activities than CLDN18.2-mBBZ CAR-T cells in the KPC1199 tumor model (p < 0.05), which was contrary to the PANC02 tumor model." (PMID 37046312, 2023). "Indeed, the application of monomeric receptors, such as PSMA or FAP radiotracers, is limited due to tumor heterogeneity or suboptimal in vivo pharmacokinetics." (PMID 37835533, 2023). "Additionally, FAP regulates tumor growth and invasiveness by increasing angiogenesis and reducing the immune system's antitumor response mediated by the STAT3/CCL2 signaling pathway." (PMID 37316886, 2023). "Our studies confirmed that FAP could be a prognostic biomarker and immunosuppressor for numerous malignancies by influencing the infiltration levels of tumor immune cells." (PMID 37490719, 2023). "For example, therapeutic approaches based on tumor vaccines or chimeric antigen receptor (CAR) T-cell therapies targeting fibroblast activation protein (FAP), a surface marker of CAF, have been shown to reactivate antitumor immune responses and inhibit tumor progression." (PMID 38235137, 2023). "Based on these results, we found that the up-regulation of FAP could promote gastrointestinal cancers progression through promoting tumor cell motility as well as macrophages infiltration and M2 polarization." (PMID 37325617, 2023). "The effect of FAP on tumor progression, immunosuppression and angiogenesis could be a consequence of its extracellular matrix remodeling capability as well as its activation of intracellular signaling." (PMID 37166418, 2023). "Promoting the differentiation of CAFs into the ADH1B+CAFs may contribute to enhancing anti-tumor immune response, while FAP+CAFs are specifically enriched in late-stage tumors and promote tumor growth." (PMID 37187731, 2023). "All mentioned evidence supports the present results that high IL-6-secreting CAFs were positive for CD10+ GPR77+ FAP+ which may correlate with drug resistance and may regulate anti-tumor immune responses." (PMID 37480115, 2023). "Similarly, the co-introduction of anti-FAP and anti-tumor CAR-T cells has also shown to enhance anti-tumor immunity in xenografted immune-deficient mouse models." (PMID 37328876, 2023). "Although a universal marker that defines all fibroblasts in the TME is lacking, numerous markers are described to be expressed by activated fibroblasts in the tumours, among which the two most prominent are fibroblast-activation protein (FAP) and alpha-smooth muscle actin (αSMA)." (PMID 36480035, 2023). "More than 28 tumor types have been proven to strongly fix a FAP-targeted 68Ga-radiopharmaceutical." (PMID 37376181, 2023). "For instance, treatment regimens could encompass CAR T-cells designed to target multiple tumor antigens, or combination treatments aimed at both cancer cells and stromal cells like FAP." (PMID 37760801, 2023). "Diversity in recruitment of FAP-positive CAFs into the tumor microenvironment could lead to differences in FAP availability and probe binding." (PMID 38026901, 2023). "In this study, we explored the expression of FAP in the tumor stroma of advanced NSCLC tissues and determined whether high expression of FAP was associated with decreased immune infiltrates, particularly on CD3 + T cells and CD8 + T cells in the TME." (PMID 35951090, 2023). "Furthermore, FAP-expressing fibroblasts were present (FAP IHC), and excessive collagen formation was found in these tumours (Sirius red)." (PMID 37408254, 2023).
tumor (continued). "Our in vitro and in vivo results show that FAP UCAR T-cells enable the reprogramming of the cold, stroma-rich TNBC TME, making the tumor susceptible to subsequent Meso UCAR T infiltration and cytotoxicity and improving the overall antitumor activity of the treatment." (PMID 37251405, 2023). "Additionally, by integrating TCGA and GTEx data, we thoroughly investigated the differential expression of FAP between 33 tumor and normal samples." (PMID 37490719, 2023). "The ultimate goal of this reported research is to develop 68Ga-labeled PSMA/FAP bispecific tracers with comparable or higher tumor uptake when compared to the monospecific tracers, [68Ga]Ga-FAPI-04 and [68Ga]Ga-HTK03041, a PSMA-targeting tracer previously reported by our group." (PMID 36770755, 2023). "In this study, we observed that FAP expression is positively correlated with endothelial cell infiltration in almost cancer types, indicating that FAP may also exert its tumor progression role by promoting angiogenesis in a wide range of cancer types." (PMID 37166418, 2023). "Thus, following confirmation of anti-CAF cytotoxicity of both FAP CAR T-cells, we next assessed their ability to make desmoplastic ‘cold’ solid tumors more susceptible to tumor antigen-directed CAR T-cells." (PMID 37251405, 2023). "Our results found that FGF20 is a downstream target of the WNT signaling in FAP(+) CAFs at EOCC tumor invasive margin and suggested that FGF20 may represent a ligand for FGF receptors." (PMID 37964075, 2023). "The results suggested that largerer tumor size (OR=4.397, p = 0.026), higher ypT stage (OR=6.260, p = 0.036), higher expression of FAP in CAF (OR=16.905, p = 0.004), and higher expression of Twist1 (OR=14.238, p = 0.001) were independent predictors for the pathological response, respectively." (PMID 37277751, 2023). "This may be due to the fibrotic reaction of tumor cells invading the peritoneum, and the target of fapi is fibroblast activating protein (FAP)." (PMID 36653862, 2023). "In addition to inhibiting FAP, the fact that FAP is restricted to the tumour tissue has been exploited to specifically deliver therapies to the TME." (PMID 35479076, 2022). "Furthermore, within the tumor, the [177Lu]Lu−iFAP/iPSMA nanosystem is additionally retained by a mechanism mediated by FAP and PSMA proteins." (PMID 36500804, 2022). "Furthermore, sex, tumor depth, lymph node status, high FAP expression, and high EGFR expression were significant prognostic factors for DFS." (PMID 36418422, 2022). "This specific therapeutic target has been optimized using FAPα in combination with survivin to design a new formulation of a DNA vaccine with a double target that promotes the infiltration of T cells to the tumor, thus regulating the tumor microenvironment." (PMID 36016136, 2022). "Both primary tumours with peritoneal metastases involvement (n = 35 regions from 12 patients), and the peritoneal metastases derived from them (n = 59), displayed significantly higher expression levels of FAP when compared to primary CRC tumours in the TCGA cohort (n = 582)." (PMID 35296803, 2022). "FAP expression was highly heterogeneous among and within individual tumours." (PMID 35296803, 2022). "Furthermore, it has been demonstrated that increasing CD8+ T cell antitumour responses using a chimeric antigen receptor (CAR) T-cell specific for FAPα can suppress the growth of a variety of subcutaneously implanted tumours in mice." (PMID 36555218, 2022). "They hypothesize that FAP-expressing CAFs interact with tumor cells and other players in the TME in differential ways according to the context, tumor stage and tissue of origin." (PMID 36428657, 2022). "Both the FGF2-neutralizing antibody and PD-166866 inhibited the expression levels of p-FGFR1 and FAPα in HSCs, suppressed the recruitment of Gr-1+ MDSCs, decreased the expression of vimentin, and increased the expression of E-cadherin in tumor cells." (PMID 35951441, 2022).